MOG (myelin oligodendrocyte glycoprotein)
Description:
Mediates homophilic cell-cell adhesion (By similarity). Minor component of the myelin sheath. May be involved in completion and/or maintenance of the myelin sheath and in cell-cell communication. (Microbial infection) Acts as a receptor for rubella virus.
Synonyms: BTN6; BTNL11; MOGIG2; NRCLP7
Tractability: Antibody: UniProt places it where antibodies can reach, with high confidence; UniProt predicts a signal peptide or a membrane-spanning region; its Gene Ontology location is reachable by antibodies, with medium confidence.
Gene: Protein-coding gene on chromosome 6 (29,656,598 to 29,674,431, forward strand). Ensembl gene ENSG00000204655.
Subcellular location: Cell membrane (Isoform 1); Cell membrane (Isoform 5); Cell membrane (Isoform 2); Cell membrane (Isoform 3); Cell membrane (Isoform 4); Cell membrane (Isoform 6); Cell membrane (Isoform 7); Cell membrane (Isoform 8); Cell membrane (Isoform 9)
Gene Ontology:
Molecular function: signaling receptor binding
Biological process: central nervous system development; regulation of cytokine production; T cell receptor signaling pathway
Cellular component: external side of plasma membrane; plasma membrane
Genetic constraint (gnomAD): Loss-of-function variants: 19 observed, 31.93 expected, observed/expected ratio (o/e) 0.6, 90% interval 0.41 to 0.87. The upper end of that interval is the gene's LOEUF score, 0.87, which puts it in group 3 of 6, group 1 being the genes least tolerant of losing a copy. Missense variants: 242 observed, 301.68 expected, observed/expected ratio (o/e) 0.8, 90% interval 0.72 to 0.89. Synonymous variants: 88 observed, 114.56 expected, observed/expected ratio (o/e) 0.77, 90% interval 0.65 to 0.92.
Homologues: Orthologues: chimpanzee MOG (98% identical), macaque MOG (96% identical), pig MOG (90% identical), rabbit MOG (87% identical), mouse Mog (85% identical), guinea pig MOG (80% identical). Paralogues in human: BTN1A1 (33% identical), BTN3A3 (32% identical), BTN3A1 (32% identical), BTN3A2 (32% identical), BTN2A1 (30% identical), BTN2A2 (30% identical), BTNL9 (29% identical), BTNL2 (28% identical), BTNL8 (28% identical), BTNL3 (26% identical), ERMAP (24% identical), CD276 (18% identical), and 3 more.
Diseases named in the same sentence as MOG in open-access papers:
MOG is named in the same sentence as 346 diseases in open-access papers, as found by Europe PMC text mining. Sharing a sentence is not in itself a finding about the gene and the disease. The quoted sentences say what the papers report.
neuromyelitis optica spectrum disorder (390 papers, 2011 to 2026). "For instance, its frequency has been reported as 72% in anti-NMDAr encephalitis, 65% during ADEM, 10% during neuromyelitis optica, 3% during MOG associated encephalomyelitis, and 12% in systemic AD with CNS involvement." (PMID 40304836, 2025). "Anti‐AQP4 antibodies are associated with neuromyelitis optica spectrum disorder; antibodies against myelin oligodendrocyte glycoprotein (MOG) are found in a similar demyelinating disorder." (PMID 40781762, 2025). "Cerebrospinal fluid (CSF) interleukin-6 (IL-6) can be markedly elevated in neuroinflammatory conditions, such as neuromyelitis optica spectrum disorder and myelin oligodendrocyte glycoprotein antibody-associated disease." (PMID 40175894, 2025). "Optic neuritis (ON) is an inflammatory condition of the optic nerve associated with demyelinating diseases like multiple sclerosis, neuromyelitis optica spectrum disorder, and myelin oligodendrocyte glycoprotein antibody-associated disease." (PMID 40206291, 2025). "Detection of antibodies against aquaporin-4 (AQP4-IgG) and myelin oligodendrocyte glycoprotein (MOG-IgG) is essential for diagnosis of AQP4-IgG+ neuromyelitis optica spectrum disorder and myelin oligodendrocyte glycoprotein antibody-associated disease." (PMID 40933287, 2025). "27,31 Brain MRI can indicate multiple sclerosis or other inflammatory demyelinating disorders (i.e. AQP4+ neuromyelitis optica spectrum disorder and myelin oligodendrocyte glycoprotein antibody-associated disease)." (PMID 39611182, 2024). "Some CNSV are combined with demyelinating lesions as overlapping syndromes, such as SLE combined with neuromyelitis optica spectrum disorders (NMOSDs) or myelin oligodendrocyte glycoprotein antibody-associated disease (MOGAD), and SS combined with NMOSD." (PMID 38605731, 2024). "Myelin oligodendrocyte glycoprotein antibody disease (MOG-AD) poses a diagnostic challenge, often masquerading as other neurological disorders such as multiple sclerosis and aquaporin-4-positive neuromyelitis optica spectrum disorder." (PMID 38975430, 2024). "MOG antibody is usually associated with neuromyelitis optica spectrum disorder and postinfectious acute disseminated encephalomyelitis." (PMID 36755772, 2023). "Patients with aquaporin-4 antibody-positive neuromyelitis optica spectrum disorder (AQP4 + NMOSD) were reported to demonstrate worse outcomes compared with patients with anti-myelin oligodendrocyte glycoprotein-associated disorders (MOGAD)." (PMID 36864239, 2023). "On the other hand, in a few instances where NMOSD criteria have not been met, ON is thought to be brought on by a condition called MOGAD (anti-MOG antibody-associated illness), which is unrelated to neuromyelitis optica (NMO) or MS." (PMID 37363580, 2023). "Aquaporin-4-antibody neuromyelitis optica spectrum disorders were diagnosed in three (2.4%, 0.26/million children/year), and relapsing myelin oligodendrocyte glycoprotein antibody-associated disease in five (4%, 0.43/million children/year)." (PMID 34693523, 2022). "It has been shown that CSF interleukin (IL)-6 is increased in neuromyelitis optica spectrum disorders (NMOSD) or in myelin oligodendrocyte glycoprotein antibody-associated disease (MOGAD) compared to MS." (PMID 35401550, 2022). "We recently found a similar impact of steroid treatment in patients with MS, AQP4-IgG+ neuromyelitis optica spectrum disorder and MOG-IgG-associated disease." (PMID 34108575, 2021). "Neuromyelitis optica spectrum disorder (NMOSD) associated with myelin oligodendrocyte glycoprotein (MOG) antibody is an immune-mediated inflammatory condition involving spinal cord and optic nerves, similar to NMOSD with aquaporin-antibody (AQP4)." (PMID 34484845, 2021). "Demyelinating optic neuritis is a classic presentation of multiple sclerosis and related conditions including neuromyelitis optica spectrum disorder and anti-myelin oligodendrocyte glycoprotein associated disease." (PMID 34863294, 2021).
neuromyelitis optica spectrum disorder (continued). "Cell-based therapies are gaining momentum as promising treatments for rare neurological autoimmune diseases, including neuromyelitis optica spectrum disorders and myelin oligodendrocyte glycoprotein antibody-associated disease." (PMID 34360690, 2021). "Optic neuritis (ON) is frequently encountered in multiple sclerosis, neuromyelitis optica spectrum disorder, anti-myelin oligodendrocyte glycoprotein associated disease, and other systemic autoimmune disorders." (PMID 34863294, 2021). "Neuromyelitis optica spectrum disorders (NMOSDs) and myelin oligodendrocyte glycoprotein-antibody-associated disease (MOGAD) are autoimmune inflammatory disorders of the central nervous system (CNS)." (PMID 33473247, 2020). "Longitudinally extensive transverse myelitis (LETM) is classically related to aquaporin (AQP4)-antibodies (Ab) neuromyelitis optica spectrum disorders (NMOSD) or more recently to myelin oligodendrocyte glycoprotein (MOG)-Ab associated disease." (PMID 32326965, 2020). "Autoantibodies against aquaporin-4 (AQP4-Ab) and myelin oligodendrocyte glycoprotein (MOG-Ab) are associated with rare central nervous system inflammatory demyelinating diseases like neuromyelitis optica spectrum disorders (NMOSD)." (PMID 32625206, 2020). "We used the search terms “neuromyelitis optica,” “neuromyelitis optica spectrum disorder,” “MOG,” aquaporin-4 antibodies,” “MRI,” “diagnostic criteria,” “therapy,” and combinations of these." (PMID 30405519, 2018). "OCB and IgG index frequencies in BCS are much more similar to those reported in neuromyelitis optica or myelin oligodendrocyte glycoprotein antibody-associated encephalomyelitis than to those in MS." (PMID 29347989, 2018). "Myelin oligodendrocyte glycoprotein immunoglobulin G1 (MOG-IgG1)-associated disease is suggested as a separate disease entity distinct from multiple sclerosis and neuromyelitis optica spectrum disorder." (PMID 30577778, 2018). "MOG-IgG obtained from neuromyelitis optica patients causes myelin changes and alters the expression of axonal proteins when injected in mouse brain." (PMID 24685353, 2014). "The clinical manifestations of overlapping syndromes were diverse; all patients met the clinical phenotype of autoimmune GFAP astrocytopathy (A-GFAP-A) and also fulfilled the diagnostic criteria for neuromyelitis optica spectrum disorders or MOG antibody-associated disorders." (PMID 40777035, 2025). "Historical and clinical data on multiple sclerosis and neuromyelitis optica spectrum disorder extend back more than a century, whereas MOG antibody-associated disease has only recently been incorporated into the spectrum of central nervous system demyelinating disorders." (PMID 40362691, 2025). "In the context of all three conditions—multiple sclerosis, neuromyelitis optica, and myelin oligodendrocyte glycoprotein antibody-associated disease—integrated biomarker platforms that synthesize fluid-based, imaging, and immunological indicators constitute the frontier of biomarker research." (PMID 40362691, 2025). "Anti-MOG is an antibody against myelin oligodendrocyte glycoproteins, a component found in the central nervous system that is associated with demyelinating autoimmune diseases such as Neuromyelitis Optica and Multiple Sclerosis." (PMID 39699422, 2024). "We searched PubMed, Embase, Google Scholar, PsycINFO, and clinicaltrials.gov using the terms ‘CAR T cell’ and ‘multiple sclerosis/MS’ or ‘neuromyelitis optica/spectrum diseases/NMOSD’ or ‘MOG-associated disease/MOGAD ‘or’ autoimmune encephalitis’ or ‘neuroimmunology’." (PMID 39276207, 2024). "It is also recognized that the pathological features associated with myelin oligodendrocyte glycoprotein antibodies are beyond the domain of neuromyelitis optica spectrum disorder and there is a separate nomenclature, namely myelin oligodendrocyte glycoprotein antibody associated disease." (PMID 37581199, 2023).
neuromyelitis optica spectrum disorder (continued). "The localization of specific brainstem lesions may also have diagnostic value in distinguishing MS from clinically similar entities like myelin oligodendrocyte glycoprotein (MOG)-associated disease or neuromyelitis optica spectrum disorder (NMOSD)." (PMID 36315254, 2023). "Our understanding of the clinical spectrum of myelin oligodendrocyte glycoprotein antibody-associated disease (MOG-AD) is in its infancy when compared to better studied central nervous system demyelinating diseases, such as multiple sclerosis (MS) and neuromyelitis optica spectrum disorder (NMOSD)." (PMID 35795797, 2022). "In typical optic neuritis and optic neuritis associated with MS, visual acuity loss is moderate, conversely, optic neuritis associated with neuromyelitis optica spectrum disorder (NMOSD) or myelin oligodendrocyte glycoprotein (MOG) often presents with severe vision loss." (PMID 33224094, 2020). "It is currently a matter of debate whether the patient suffered from a neuromyelitis optica spectrum disorder (NMOSD) or a myelin oligodendrocyte glycoprotein-antibody-associated disease (MOGAD)." (PMID 33473247, 2020). "Although LETM is classically related to AQP4-antibodies (Ab) neuromyelitis optica spectrum disorders (NMOSD) or more recently to MOG-Ab associated disease, alternative diagnoses have to be excluded such as vascular, granulomatosis, paraneoplastic, metabolic, and infectious diseases." (PMID 32326965, 2020). "Due to the excellent immunosuppressive effects and economical price, MMF has been increasingly used in the treatment of neurological diseases such as neuromyelitis optica spectrum disorders, myelin oligodendrocyte glycoprotein (MOG)-associated disease, and multiple sclerosis." (PMID 33240207, 2020). "Antibodies with specificity for myelin oligodendrocyte glycoprotein (MOG) are implicated in ON, as well as in ON associated with neuromyelitis optica spectrum disorder (NMOSD) in cases where immunoglobulin (Ig) G antibodies against the water channel aquaporin-4 are undetectable." (PMID 30857557, 2019). "Previous reports of patients with myelitis associated with rheumatologic disease may have had unrecognized aquaporin-4 (AQP4)-IgG seropositive neuromyelitis optica spectrum disorder (NMOSD) or myelin oligodendrocyte glycoprotein (MOG)-IgG–associated disease (MOGAD)." (PMID 39442039, 2025). "However, the prevalence range is wide, with around 95% in MS, and for example 16.4% in neuromyelitis optica, 6–17% in myelin oligodendrocyte glycoprotein antibody-associated disease, 25% in Sjögren’s syndrome, and 29–58% in acute disseminated encephalomyelitis." (PMID 36696385, 2023). "Interestingly, CSF IL-6 concentration could help identify neuromyelitis optica spectrum disorder, myelin oligodendrocyte glycoprotein antibody-associated disease, and central nervous system (CNS) vasculitis." (PMID 35401550, 2022). "Based on clinical, immunological and histopathological evidence, MOG-IgG-associated encephalomyelitis (MOG-EM) has emerged as a distinct disease entity different from multiple sclerosis (MS) and aquaporin-4-antibody-positive neuromyelitis optica spectrum disorder (NMOSD)." (PMID 32055995, 2020). "Multiple sclerosis (MS), neuromyelitis optica spectrum disorder (NMOSD), and myelin oligodendrocyte glycoprotein-associated disease (MOGAD) are the major types of demyelinating disorders of the central nervous system (CNS)." (PMID 42043479, 2026). "Neuromyelitis optica spectrum disorders (NMOSD) and myelin oligodendrocyte glycoprotein (MOG) antibody-associated disease (MOGAD) are autoimmune inflammatory disorders of the central nervous system (CNS)." (PMID 40777014, 2025). "Neuromyelitis optica spectrum disorders (NMOSD) and myelin oligodendrocyte glycoprotein antibody-associated disease (MOGAD) are autoimmune central nervous system disorders with poorly understood immune pathways." (PMID 40777014, 2025).
neuromyelitis optica spectrum disorder (continued). "While ON has historically been linked to MS, the etiological spectrum has expanded with the recognition of neuromyelitis optica spectrum disorder (NMOSD) and myelin oligodendrocyte glycoprotein (MOG) antibody-associated disease (MOGAD)." (PMID 41414995, 2025). "Other potential autoimmune etiologies were less likely, given that the patient's neuromyelitis optica, myelin oligodendrocyte glycoprotein, and serum/CSF autoimmune encephalopathy panels were negative." (PMID 40995154, 2025). "Background and Objectives: Neuromyelitis optica spectrum disorder (NMOSD) and MOG antibody-associated disease (MOGAD) are distinct autoimmune demyelinating disorders of the central nervous system, characterized by different pathological and clinical features." (PMID 41155859, 2025). "Previous studies have also reported eosinophils in patients diagnosed with neuromyelitis optica spectrum disorder (NMOSD), as well as those with myelin oligodendrocyte glycoprotein antibody-associated disease (MOGAD)." (PMID 41142784, 2025). "Neuromyelitis optica spectrum disorders (NMOSD) and myelin oligodendrocyte glycoprotein (MOG) antibody-associated disorders (MOGAD) are two immune-mediated inflammatory demyelinating diseases of the CNS." (PMID 40777035, 2025). "Potential differentials included GFAP astrocytopathy, anti-NMDAR encephalitis, MOG antibody disease, and neuromyelitis optica spectrum disorder (NMOSD)." (PMID 41497949, 2025). "Anti-myelin oligodendrocyte glycoprotein (MOG) antibodies and aquaporin-4 antibodies were tested to exclude neuromyelitis optica spectrum disorder (NMOSD) and MOG antibody-associated disease; both results came back negative." (PMID 41280952, 2025). "The role of soluble biomarkers extends beyond MS, with evidence increasingly supporting their utility in related disorders such as Neuromyelitis Optica Spectrum Disorder (NMOSD) and Myelin Oligodendrocyte Glycoprotein-Associated Disease (MOGAD)." (PMID 40254498, 2025). "Neuromyelitis optica spectrum disorder (NMOSD) and myelin oligodendrocyte glycoprotein antibody-associated disease (MOGAD) are distinct autoimmune demyelinating disorders of the central nervous system, primarily affecting the optic nerves and spinal cord." (PMID 41155859, 2025). "Two patients from the first cohort developed alternative diagnoses during follow-up (1 each with neuromyelitis optica spectrum disorder [NMOSD] and myelin oligodendrocyte glycoprotein antibody-associated disorder [MOGAD]) and were excluded." (PMID 40036713, 2025). "AQP4-Ab-positive ON is classified as neuromyelitis optica spectrum disorder (NMOSD), a condition distinct from multiple sclerosis (MS), whereas MOG-Ab-positive ON is classified as MOG-IgG associated disorder (MOGAD)." (PMID 40377800, 2025). "Neuromyelitis optica spectrum disorder (NMOSD) and myelin oligodendrocyte glycoprotein antibody-associated disease (MOGAD) are demyelinating diseases of the central nervous system." (PMID 41409219, 2025). "Serum studies were sent for neuromyelitis optica, myelin oligodendrocyte glycoprotein, antineutrophil cytoplasmic antibody, and serum autoimmune encephalopathy panels." (PMID 40995154, 2025). "Among these, the most common ones, which make the subject of the current paper, are multiple sclerosis (MS), neuromyelitis optica spectrum disorder (NMOSD), and myelin oligodendrocyte glycoprotein-associated disease (MOGAD)." (PMID 40362691, 2025). "These include Alzheimer’s disease, Parkinson’s disease, multiple sclerosis, neuromyelitis optica, and myelin oligodendrocyte glycoprotein antibody disease." (PMID 39766465, 2024). "The main clinical disorders involved in this area of neurology are multiple sclerosis (MS), neuromyelitis optica spectrum disorder (NMOSD), and myelin oligodendrocyte glycoprotein-immunoglobulin G (MOG-IgG)-associated disorders (MOGADs)." (PMID 39675357, 2024).